REG3G (regenerating family member 3 gamma)
Diseases named in the same sentence as REG3G in open-access papers (continued):
Sharing a sentence is not in itself a finding about the gene and the disease.
intestinal infection (3 papers, 2015 to 2023). "Reg3a and Reg3g are highly expressed upon bacterial colonization of the gut and during intestinal infection and inflammation, thereby contributing to the spatial segregation of intestinal bacteria and the epithelium." (PMID 37170509, 2023). "Specifically, we focused on the Gram-positive selective antimicrobial peptide REG3γ and on mucin, two host intestinal defense factors that have been shown to be important for the control of gastrointestinal infections." (PMID 30622186, 2019).
type 1 diabetes (3 papers, 2017 to 2022). "Unlike that in normal human epithelial cells, the expression of REG3A and Reg3γ mRNA was significantly decreased in the skin of diabetic patients and streptozotocin (STZ)-induced experimental type 1 diabetic T1D mice, respectively." (PMID 34811636, 2022).
acute pancreatitis (2 papers, 2020 to 2021). An acute inflammatory process that leads to necrosis of the pancreatic parenchyma. "Reg3a has been shown to regulate keratinocyte proliferation and differentiation after skin injury via Reg-Extl3-PI3K-Cyclin D1 pathway, while Reg3g downregulates the Stat3-Socs signaling which may result in enhanced apoptosis in acute pancreatitis." (PMID 34926699, 2021).
endotoxemia (2 papers, 2019 to 2025). "Loss of REG3β or REG3γ did not cause more severe liver disease than in their WT littermates, despite elevated endotoxemia in Reg3γ-deficient mice." (PMID 30392013, 2019). "Studies reveal that ethanol decreases Akkermansia in mice, but IL‐22 treatment can elevate this symbiont, restoring alcohol‐reduced Reg3γ and α‐defensin levels, restoring intestinal barrier function, and reducing endotoxemia." (PMID 41362700, 2025).
ileitis (2 papers, 2024 to 2025). "ASF-SKG ileum expressed higher levels of Ocln and lower Reg3g and Reg3b than GF or monoassociated SKG ileum, consistent with their lack of ileitis and lower ER stress and Il23a levels." (PMID 40762957, 2025).
influenza (2 papers, 2015 to 2020). An acute viral infection of the respiratory tract, occurring in isolated cases, in epidemics, or in pandemics; it is caused by serologically different strains of viruses (influenzaviruses) designated A, B, and C, has a 3-day incubation period, and usually lasts for 3 to 10 days. "Knock-out mice carrying a mutation in the Reg3g gene on a C57BL/6 N background were infected with influenza PR8M." (PMID 26329040, 2015).
liver disease (2 papers, 2019 to 2025). "We have demonstrated that ethanol-fed Reg3γ−/− and Reg3β−/− mice have increased susceptibility to ethanol-induced liver disease, in association with increased mucosa-associated bacteria and more translocation of bacteria to the liver." (PMID 30392013, 2019). "In line, intestine-specific overexpression of Reg3γ protects mice against ethanol-induced liver disease by maintaining an inner mucus layer devoid of bacteria and reducing bacterial translocation." (PMID 30392013, 2019).
Methicillin-Resistant Staphylococcus Aureus Pneumonia (2 papers, 2017 to 2020). Pneumonia that is caused by Staphylococcus aureus and is resistant to methicillin treatment. "STAT3-mediated induction of the antimicrobial protein REG3G is required for host defense against methicillin-resistant Staphylococcus aureus pneumonia." (PMID 33488611, 2020). "In our MRSA pneumonia model, we observed a lower level of Reg3γ mRNA expression in the neonate at baseline compared to the adult mice." (PMID 28060871, 2017).
Salmonella Infections (2 papers, 2021 to 2022). Infections with bacteria of the genus SALMONELLA. "In this context, upregulation of S100a9 and Reg3g as well as elevated IL-22 serum levels during Salmonella infection suggesting alternative signaling pathways potentially mediated via STAT348." (PMID 34497340, 2022).
Stroke (2 papers, 2023 to 2025). Sudden impairment of blood flow to a part of the brain due to occlusion or rupture of an artery to the brain. "Smoking may dysregulate inflammation-related genes (e.g., TSG6, involved in intestinal muscle repair) and barrier function proteins (e.g., REG3G) in patients with stroke, impairing anal sphincter synthesis of patients with stroke and increasing FI risk." (PMID 41383342, 2025). "Instead, ovariectomized female mice had an up-regulation of AMP genes such as Reg3b and Reg3g (P = .0177 for Reg3b and P = .0228 for Reg3g), similar to the post-stroke response seen in young males." (PMID 37910478, 2023).
type 2 diabetes (2 papers, 2016 to 2022). "For example, microarray studies performed on human pancreatic islets isolated from patients with type 2 diabetes and glucose-tolerant controls identified, among other changes, overexpression of ENPP1, TSPAN4, TSPAN8, CSRP1, REG3A and REG3G, genes that were also upregulated with age in our study." (PMID 26699651, 2016).
adenoma (1 paper, 2025). A neoplasm arising from the epithelium. "Moreover, Reg3γ and Reg3β were also downregulated (1.2log2FC) in Smad4Δ/Δ adenomas and as both genes are important for epithelial defence against bacterial invasion." (PMID 40348815, 2025).
alcoholic hepatitis (1 paper, 2022). Acute hepatitis resulting from ingestion of alcohol. "The overexpression of Reg3γ protected mice from alcoholic hepatitis and reduced bacterial translocation." (PMID 35491818, 2022).
alcoholic liver diseases (1 paper, 2023). A disorder caused by damage to the liver parenchyma due to alcohol consumption. "L. reuteri was designed to overexpress the interleukin-22 (IL-22) gene, which increased REG3G abundance in the intestine, reduced inflammation and damage in liver using an alcoholic liver disease mouse model." (PMID 37169742, 2023).
asthma (1 paper, 2021). "Interestingly, a previous study demonstrated that Reg3γ induced by IL-22 inhibits allergic airway inflammation in asthma models." (PMID 34867960, 2021). "A previous study in a house dust mite (HDM)-induced asthma model demonstrated that allergic airway inflammation and AHR were exacerbated by neutralization of allergen challenge-induced Reg3γ production in the airway." (PMID 34867960, 2021).
autoimmune myocarditis (1 paper, 2021). Autoimmune myocarditis is an autoimmune disease that affects the heart. "Increased Reg3γ expression was found in hearts of pressure overloaded rats and elevated Reg3β levels were determined in animal models of experimental autoimmune myocarditis." (PMID 33923774, 2021).
cardiac sarcoidosis (1 paper, 2021). Sarcoidosis affecting the tissues of the heart. "In order to clarify whether the formation of granulomata occurs via accumulation of chemoattracted macrophages we determined the regenerating islet-derived protein (Reg) family members Reg3A and Reg3γ in the myocardium of patients with cardiac sarcoidosis." (PMID 33923774, 2021). "The myocardial accumulation of monocyte/macrophage-derived OSM, along with the expression of Reg3A and Reg3γ in remodeling cardiomyocytes, emphasizes the prevalence of an OSM/OSMR/Stat3/Reg axis in the development of cardiac sarcoidosis." (PMID 33923774, 2021).
Chlamydia infection (1 paper, 2025). "Moreover, a consistent downregulation of antimicrobial genes such as Reg3b and Reg3g from the inactivated to the virulent Chlamydia infection stages indicates a weakened defensive capability of the host against pathogen invasion." (PMID 40786607, 2025).
cystic fibrosis (1 paper, 2006). Autosomal recessive disorder caused by pathogenic variants in the CFTR gene (cystic fibrosis transmembrane conductance regulator), which encodes a chloride and bicarbonate channel expressed in epithelial cells, and follow the diagnosis criteria. "The cystic fibrosis mouse pancreas has constitutively elevated expression of the Reg/PAP cell stress genes (60-fold greater Reg3α, and 10-fold greater PAP/Reg3β and Reg3γ)." (PMID 16700916, 2006). "Therefore, we took advantage of the CFTR (cystic fibrosis transmembrane conductance regulator) null mouse (CF mouse), which has constitutively elevated expression levels of the Reg3α, PAP/Reg3β and Reg3γ genes." (PMID 16700916, 2006).
escherichia coli infection (1 paper, 2023). Infection with the organism Escherichia Coli. "For instance, Reg3γ expression is increased in the urinary tract following uropathogenic Escherichia coli infection, while Reg3γ fails to kill pathogenic E. coli, and Reg3γ deficiency does not increase susceptibility." (PMID 37524871, 2023).
food allergy (1 paper, 2025). Gastrointestinal disturbances, skin eruptions, or shock due to allergic reactions to allergens in food. "In a food allergy mouse model, disruption of the tryptophan pathway suppressed Reg3g and IL-22 expression and disturbed intestinal immune homeostasis." (PMID 41395465, 2025).
gastritis (1 paper, 2012). Inflammation of the stomach. "Therefore we determined REG3γ expression levels in gastric epithelial biopsies collected from patients (n = 24) showing histopathologic evidence of gastritis with predetermined H. pylori infection and CagA cytotoxin status." (PMID 22312430, 2012).
glioma (1 paper, 2022). A benign or malignant brain and spinal cord tumor that arises from glial cells (astrocytes, oligodendrocytes, ependymal cells). "Knowing that REG3γ is involved in shaping the gut microbiota composition, we speculated that late-stage glioma could be associated with a shift in bacterial metabolites, which are important mediators allowing the microbiota to modulate host physiology, including the brain." (PMID 35448477, 2022). "Our gene expression analysis showed that the antimicrobial peptide Reg3g mRNA is downregulated in the jejunum and ileum of mice with late-stage glioma." (PMID 35448477, 2022). "Reg3g downregulation in the absence of drastic inflammation may thus be a characteristic of a glioma-associated pre-cachexic state." (PMID 35448477, 2022).
graft versus host disease (1 paper, 2019). An immune system disorder that occurs after allogeneic hematopoietic stem cell transplant and is a reaction of donor immune cells against host tissues. "Furthermore, the increase in intestinal REG3γ suppresses the apoptosis of stem cells and Paneth cells induced by graft-versus-host disease, suggesting that REG3γ has an important role in small intestinal barrier function." (PMID 31817820, 2019).
gram-positive bacterial infections (1 paper, 2018). Infections caused by bacteria that retain the crystal violet stain (positive) when treated by the gram-staining method. "Moreover, the production of the antimicrobial peptides Reg3β and Reg3γ, known to bind bacteria peptidoglycans and protect host against Gram-positive bacterial infection, was significantly reduced in the absence of Saa3." (PMID 30008720, 2018).
heart failure (1 paper, 2016). Inability of the heart to pump blood at an adequate rate to meet tissue metabolic requirements. "Since chronic inflammation is characteristics also for heart failure, the aim of this study was to characterize Reg3γ expression in cardiac inflammatory conditions." (PMID 27798352, 2016).
injury (1 paper, 2023). Damage inflicted on the body as the direct or indirect result of an external force, with or without disruption of structural continuity. "The authors found that treatment with IL-22-producing L. reuteri upregulated intestinal Reg3γ levels and alleviated alcohol-induced liver injury." (PMID 37908362, 2023).
lung carcinoma (1 paper, 2024). "In this study, we also found that several genes related to the inflammatory response, lymphocyte activation and innate immune response in the mucosa (Hp/Reg3g/Nupr1/Adam8/Cd55/Cfh/Ednrb) were upregulated in mice with EGFRL858R*PTEN-/- induced lung cancer." (PMID 38499532, 2024).
malnutrition (1 paper, 2019). Inadequate nutrition resulting from poor diet, malabsorption, or abnormal nutrient distribution. "Nevertheless, our study is the first to our knowledge to uncover how maternal malnutrition alters expression levels of AMPs in near-term fetuses and is the first to assess Reg3g mRNA expression in fetal tissues." (PMID 31248104, 2019).
myocardial infarction (1 paper, 2016). Gross necrosis of the myocardium, as a result of interruption of the blood supply to the area, as in coronary thrombosis. "Reg3γ expression was studied in experimental rat models of myocardial infarction (MI) and pressure overload in vivo." (PMID 27798352, 2016).
parasite infection (1 paper, 2015). "Germ-free mice mono-colonized with SFB have been shown to induce Reg3γ, suggesting that the reduced Reg3γ expression in mice infected with N. brasiliensis was associated with lower SFB colonization or with distinct host cytokine regulatory pathways activated by parasite infection." (PMID 26377648, 2015).
Rotavirus infection (1 paper, 2024). Infection with any of the rotaviruses. "For example, during rotavirus infection there is upregulation of type I IFN response genes (many of which are also regulated by IFN-γ) in IEC and expression of the anti-bacterial genes Reg3b and Reg3g are increased in Salmonella-infected mice." (PMID 38718306, 2024).
stomach tumor (1 paper, 2013). "The present results indicate the possibility that Reg3g is also involved with progression of stomach tumor." (PMID 23899160, 2013).
infection (32 papers, 2007 to 2026). The state of being infected such as from the introduction of a foreign agent such as serum, vaccine, antigenic substance or organism. "Some antibiotics have been found to hinder immune responses, thus increasing susceptibility to infection; for example, vancomycin, neomycin, and metronidazole have been shown to effectively reduce the expression of REG3γ, a C-type lectin." (PMID 39201552, 2024). "Gastrointestinal delivery of recombinant REG3G decreased lung inflammatory gene expression and protected Il22−/− mice from weight-loss during infection." (PMID 33488611, 2020). "Correspondingly, transcription of Reg3γ as well as the genes encoding the antimicrobial factors S100a8 and S100a9 was also strongly induced (100-fold) during infection, potentially to promote host defense." (PMID 31848276, 2019). "The specific antimicrobial protein encoded by REG3G is released by different types of small intestinal cells during infection but under prolonged stimulation its presence is depleted due to prolonged release." (PMID 30161141, 2018). "Infection of WT mice led to a modest increase in the transcription of genes encoding antimicrobial peptides (mCRAMP, Reg3γ, β-defensin III) and chemokines (MCP1 and MIP2α)." (PMID 23950714, 2013). "We could observe only minor differences in the numbers of mucosal macrophages or neutrophil granulocytes or in mRNA copy numbers of inflammatory markers like S100a9 and Reg3g during the course of infection between control and double deficient mice." (PMID 34497340, 2022). "Il22−/− mice displayed lower expression of Reg3b and Reg3g both at baseline and post-infection compared to Il22+/+ mice." (PMID 41361166, 2025). "In contrast to Lyz1, mature SAL clusters showed elevated abundances of Reg3g, Mptx2, and Mmp7, genes known to enrich in Paneth cells, especially during infection." (PMID 38823640, 2024). "Reg3a and Reg3g are C-type lectins expressed in the intestinal epithelial cells and secreted into the intestinal lumen and exert bactericidal action, thus Reg3a and Reg3g were considered to provide protection against infection with enteropathogenic bacteria." (PMID 37170509, 2023). "As a critical component of intestinal resistance to infection by enteropathogenic bacteria, Paneth cells secrete antimicrobial peptides, such as cryptdin, defensin, and Reg3γ." (PMID 34804005, 2021). "Reg3γ production is increased by oral L. monocytogenes infection, thereby contributing to the protection against the infection." (PMID 34012449, 2021). "Yet it is not clear how these data compare with our, as the authors focused on IL-33 and REG3γ at steady-state, in cell culture conditions, and at the late phase of CR infection when the bacteria are almost cleared in WT mice." (PMID 33654214, 2021). "Even at the late phase of infection (28 dpi), Reg3g, Reg3b and Ubd were significantly increased relative to those in uninfected GF mice, and the expression levels of these genes were comparable with those in SPF mice." (PMID 34012449, 2021). "Following CR infection, the upregulation of the antimicrobial peptide REG3γ in the colon was impaired by concomitant IL-33 application." (PMID 33654214, 2021). "In contrast, mice treated with IL-33 during infection showed a substantial reduction in Reg3γ expression." (PMID 33654214, 2021). "In saline-pretreated mice, SL1344 infection resulted in a significant induction of Reg3γ (3.8-fold), Defa1 (6-fold), MMP-7 (2.6-fold), and Ang-4 (8.6-fold) expression." (PMID 29616040, 2018). "Following infection, both neonate and adult mice exhibited an increase in Reg3γ at 6 hr pi which continued to increase through 24 hr." (PMID 28060871, 2017). "At the peak of the infection, genes related to antimicrobial defense and barrier function, including Reg3a, Reg3g, Defb37, Defb40, Claudin-8, and Claudin-15, also showed altered expression, suggesting weakened antimicrobial protection and impaired tight junction integrity." (PMID 40630939, 2025).